EZH2 (enhancer of zeste 2 polycomb repressive complex 2 subunit)
Diseases named in the same sentence as EZH2 in open-access papers (continued):
Sharing a sentence is not in itself a finding about the gene and the disease.
renal fibrosis (28 papers, 2016 to 2025). A final common manifestation of a wide variety of chronic kidney diseases characterized by glomerulosclerosis and tubulointerstitial fibrosis. "Compounds such as gambogenic acid, salvianolic acid B, and emodin have emerged as potential therapeutic agents against renal fibrosis due to their ability to inhibit EZH2 activity and its associated epigenetic marker, H3K9me3." (PMID 38929505, 2024). "Up to now, EZH2 has been implicated in kidney injury and renal fibrosis via multiple pathways." (PMID 40478495, 2025). "The results from this study indicate that the manipulation of the association between SMAD3 and EZH2 may be a useful therapeutic strategy for the resolution of renal fibrosis." (PMID 36435939, 2022). "Thus, EZH2 mediated epigenetic gene regulation could be a mechanism underlying the role of Tan-I in renal fibrosis." (PMID 35439976, 2022). "It has been reported that the activation of enhancer of zeste homolog 2 (EZH2) leads to renal fibrosis by activating multiple signaling pathways." (PMID 41426560, 2025). "Increasing evidence suggests that EZH2 plays a pivotal role in renal fibrosis by regulating EMT and activating M2 macrophage polarization." (PMID 40478495, 2025). "Mechanically, our study identifies ZLD1039 as a potential anti-fibrotic therapeutic agent that attenuates renal fibrosis by inhibiting EZH2/H3K27me3 and up-regulating LATS1, thereby preventing YAP nuclear translocation." (PMID 40478495, 2025). "In this study, we established a renal fibrosis model via UUO and subsequently evaluated the expression level of EZH2, proteins associated with the Hippo signaling pathway, inflammatory cytokines, and fibrosis maker proteins in UUO kidney tissues." (PMID 40478495, 2025). "Enhancer of zeste homolog 2 (EZH2) exhibits high expression level in renal fibrosis induced by unilateral ureteral obstruction (UUO), yet the interplay between YAP and EZH2 in renal fibrosis remains to be elucidated." (PMID 40478495, 2025). "In our study of UUO-induced renal fibrosis, inhibiting EZH2 with ZLD1039 restored LATS1 expression at both 7 and 14 days, indicating that LATS1 plays a protective role in renal fibrosis." (PMID 40478495, 2025). "In summary, EZH2 appears to play a multifaceted role in promoting renal fibrosis through several complex pathways." (PMID 38929505, 2024). "Targeted inhibition of EZH2 is emerging as a promising therapeutic avenue to attenuate renal fibrosis with potential clinical benefits." (PMID 38929505, 2024). "The activation of several intracellular signaling pathways that leads to renal fibrosis and the epithelial-mesenchymal transition is modulated by EZH2 and H3K27me3." (PMID 35883846, 2022). "Blockade of EZH2 plays a protective role in obstructive nephropathy, hyperuricemic nephropathy and lupus nephritis, attenuating renal fibrosis and alleviating renal dysfunction." (PMID 35559246, 2022). "Blockage of EZH2 with pharmacologic inhibitor 3-deazaneplanocin A or siRNA attenuates progression of renal fibrosis." (PMID 35906216, 2022). "There is a wealth of data on the role of EZH2 in promoting renal fibrosis in acute kidney injury induced by ischemia-reperfusion, folic acid, or unilateral ureteral obstruction." (PMID 35906216, 2022). "Further experiments demonstrated that the specific histone methyltransferase for H3K27me is the enhancer of zeste homolog 2 (Ezh2), which can accelerate the process of renal fibrosis." (PMID 35130617, 2022). "Multimodal single-cell analysis on iPSC-derived kidney organoids shows that inhibiting EZH2 attenuates TGFβ1-induced fibrotic gene expression and changes in chromatin accessibility, highlighting a potential therapeutic strategy for renal fibrosis." (PMID 36435939, 2022). "Recently, the role of DZNep (a histone methyltransferase EZH2 inhibitor) in repressing pulmonary and renal fibrosis was verified." (PMID 34040893, 2021).
renal fibrosis (continued). "Recent studies have demonstrated that EZH2 plays a critical role in the development of renal fibrosis." (PMID 33679454, 2021). "This is in sharp contrast to the role of the H3K27me3 methyltransferase EZH2, which induces renal fibroblast activation and renal fibrosis." (PMID 33456568, 2021). "Coincident with H3K27me3 alterations, we also observed a decrease of renal fibrosis with EZH2 inhibition and an increase of renal fibrosis with JMJD3 blockade." (PMID 33456568, 2021). "For example, Zhou’s study shows that in a renal fibrosis model, EZH2 depletion alleviates renal fibrosis." (PMID 32508971, 2020). "In a murine model of renal fibrosis induced by unilateral ureteral obstruction, EZH2 is expressed in myofibroblasts and injured renal tubular cells." (PMID 31866860, 2019). "EZH2 was shown to play an important role in the development of renal fibrosis by downregulating expression of Smad7 and PTEN to activate profibrotic signaling pathways." (PMID 27823969, 2016). "Hence, it is valuable to further investigate the role of EZH2 in CaOx-induced kidney injury and renal fibrosis by regulating EndMT." (PMID 38169402, 2024). "What’s more interesting, Targeted inhibition of EZH2 may improve renal fibrosis after acute kidney injury by counteracting partial EMT and blockade of M2 macrophage polarization." (PMID 39308866, 2024). "Furthermore, EZH2 promoted renal fibrosis by inhibiting PTEN expression and activating STAT3 and ERK1/2 phosphorylation." (PMID 38929505, 2024). "Therefore, we used EZH2 specific inhibitor (3-DZNeP) and EZH2 conditional knockout mice to explore the role and mechanism of EZH2 in renal fibrosis after acute kidney injury in IR and FA mice models (two common models used for studying AKI-CKD transition)." (PMID 37029114, 2023). "SAB might have therapeutic potential on renal fibrosis of CKD through inhibiting EZH2, which encourages further clinical trials." (PMID 36524761, 2023). "Previous studies of our research group have revealed that blockade of EZH2 protects against AKI and EZH2 could sustainably promote the progression of renal fibrosis in CKD mice (renal injury induced by hyperuricemia and UUO)." (PMID 37029114, 2023). "To test this hypothesis, we first examined the effect of GSKJ4, a specific JMJD3 inhibitor, on the development of renal fibrosis in the same UUO model used for uncovering the anti-fibrotic effect of EZH2 inhibition." (PMID 33456568, 2021). "Thus, H3K27me3 seems to be functionally linked to the fibrotic process and plays an essential role in transmitting activation of JMJD3 and EZH2 to renal fibrosis." (PMID 33456568, 2021). "Thus, targeted inhibition of EZH2 might be a novel therapy for ameliorating renal fibrosis after acute kidney injury by counteracting partial EMT and blockade of M2 macrophage polarization." (PMID 37029114, 2023). "Moreover, EZH2 activation has been reported to contribute to renal EMT and fibrosis through activating multiple signaling pathways, which suggests that EZH2 might be a therapeutic target for treatment of renal fibrosis." (PMID 35264108, 2022). "Targeting EZH2 has been shown to regulate renal epithelial-mesenchymal transition (EMT) and thereby slow the progression of renal fibrosis." (PMID 41311720, 2025). "They found that GA promotes Smad7 transcription by reducing EZH2 and H3K27me3 levels, which in turn suppresses the TGF-β/Smad3 signaling pathway, attenuating renal fibrosis." (PMID 41311720, 2025). "Research has demonstrated that EZH2 can epigenetically regulate and downregulate SLC7A11 expression, leading to renal fibrosis." (PMID 40249927, 2025). "In summary, the initial EZH2-mediated reduction in LATS1 likely contributes, at least in part, to YAP activation in UUO-induced renal fibrosis." (PMID 40478495, 2025).
renal fibrosis (continued). "This study also found that in RAW cells, inhibition of EZH2 suppressed the p-Stat6 and PI3K/AKT pathway, inhibited M2 macrophage polarization, and reduced MMP-9 secretion, providing a countermeasure against renal fibrosis." (PMID 38929505, 2024). "Several studies have shown that EZH2 expression levels are upregulated in numerous animal models of kidney injuries, including AKI, renal fibrosis, lupus nephritis, and renal tumors." (PMID 38169402, 2024). "EZH2 inhibitors are reported to exert therapeutic effects on various kidney diseases, including renal cell carcinoma, AKI, renal fibrosis, diabetic nephropathy, lupus nephritis, and renal transplant rejection." (PMID 38169402, 2024). "Previous studies of our research group have revealed that EZH2 is highly expressed in the kidney of AKI mice and can sustainably promote the progression of renal fibrosis in CKD mice." (PMID 37029114, 2023). "The pharmacological and/or genetic inhibition of EZH2 can alleviate AKI, renal fibrosis, and LN, but potentiate podocyte injury in animal models, suggesting that the functional role of EZH2 varies with renal cell type and disease model." (PMID 33679454, 2021). "Recent studies have shown that EZH2 expression and activity are also increased in several animal models of kidney injury, such as acute kidney injury (AKI), renal fibrosis, diabetic nephropathy, lupus nephritis (LN), and renal transplantation rejection." (PMID 33679454, 2021). "Collectively, these data suggest that EZH2 is critically involved in the regulation of renal fibroblast activation, partial EMT and renal fibrosis." (PMID 31866860, 2019). "To determine whether the anti-fibrotic effect of ZLD1039 is mediated by EZH2 inhibition, we examined the mRNA and protein expression levels of EZH2 in the kidneys of rats with UUO-induced renal fibrosis." (PMID 40478495, 2025). "Importantly, we propose that EZH2 and H3K27me3 inhibit LATS1 expression and activation, leading to reduced p-YAP levels and promoting YAP nuclear translocation, thereby regulating renal fibrosis." (PMID 40478495, 2025). "This mechanistic link between EZH2 and YAP provides a fresh perspective on treating renal fibrosis." (PMID 40478495, 2025). "Thus, our data highlight the protective role of EZH2 and H3K27me3 in proximal tubular cells against initiation of EMT, renal fibrosis, tubule interstitial fibrosis, and tubular hypertrophy." (PMID 41227374, 2025). "Additionally, EZH2, through activation of the AKT/mTOR and β-catenin pathways, promotes RTCs EMT and cell cycle arrest to propel renal fibrosis." (PMID 38929505, 2024). "Furthermore, dznep, a specific inhibitor of Ezh2, H3K27 methyltransferase, was revealed to effectively prevent renal fibrosis in mice models of UUO and the transition from AKI to CKD." (PMID 38542060, 2024). "On the other hand, it also has been shown that EZH2 mediates the development of renal fibrosis by down-regulating the expression of Smad7, a negative regulator of the TGF-β signaling pathway." (PMID 30539787, 2019). "Therefore, we hypothesized that after AKI injury, EZH2 regulates PTEN transcription in TECs, thereby affecting its expression, and the subsequently phosphorylation of EGFR to regulate renal fibrosis." (PMID 37029114, 2023). "Therefore, targeting EZH2 may be a potential approach for the treatment of renal fibrosis, AKI and acute rejection after transplantation, but not for diabetic nephropathy." (PMID 31866860, 2019).
diabetes (27 papers, 2013 to 2025). "Loss of enhancer of zeste homolog 2 (EZH2) decreased H3K27me3 levels in podocytes of models with diabetes, causing the activation of Notch signaling and podocyte dedifferentiation." (PMID 36787250, 2023). "As our previous study indicates a possible role of EZH2 in diabetes-associated inflammatory switch of endothelial cells, EZH2 indeed is also reported to be an important modulator of EndMT during both development and disease." (PMID 35392173, 2022). "Furthermore, sex-specific differences in basal EZH2 and H3K27me3 levels suggest that female mice may be more resilient under non-diabetic conditions but more susceptible to epigenetic dysregulation during diabetes, which requires further investigation." (PMID 41227374, 2025). "The aim of this study was to investigate the role of AGEs and diabetes on the epigenetic modifications of EZH2 and H3K27me3 in proximal tubular cells and in diabetic (db/db) mice." (PMID 41227374, 2025). "Our findings underscore the role of the USP7/Ezh2 axis in maintaining tolerogenic DC functions that are required to tailor adaptive immune response and diabetes protection in NOD mice." (PMID 40247205, 2025). "These additional findings pave the way for pilot preclinical studies targeting EZH2-mediated H3K27me3 signature with GSK126 in the setting of diabetes." (PMID 38580969, 2024). "Accordingly, EZH2 silencing has been found to improve cardiac function and prevent cardiomyocyte apoptosis in experimental diabetes." (PMID 38580969, 2024). "BRD7 suppressed Clusterin expression via modulating Clusterin promoter hypermethylation in an EZH2 dependent manner, thereby suppressing AMPK signaling to facilitate ferroptosis and induce diabetes-associated testicular damage." (PMID 38992588, 2024). "Our data demonstrated that both AGEs/diabetes and hypoxia cause a reduction in NIPP1 and EZH2 expression in podocytes, which goes along with lower H3K27me3 levels." (PMID 37760919, 2023). "EZH2 is a catalytic subunit of polycomb repressive complex 2 and has been reported to have a role in podocytes injuries and oxidative stress in diabetes." (PMID 37735624, 2023). "The results of the present study showed that diabetes upregulated the expression of EZH2, and their downstream expression of H3K27me3." (PMID 37735624, 2023). "The aim of this study is to investigate the underlying role of calcineurin/nuclear factor of activated T cell 3 (CaN/NFATc3) pathway and the Enhancer of zeste homolog 2 (EZH2) in diabetes-related myocardial fibrosis." (PMID 37735624, 2023). "In conclusion, the present study demonstrated that diabetes promotes myocardial fibrosis by activating the CaN/NFATc3/EZH2 pathway." (PMID 37735624, 2023). "Mice with beta-cell specific deletion of Ezh2 display reduced beta-cell proliferation and mass, resulting in hyperglycemia and diabetes." (PMID 35602600, 2022). "Of significance, a single injection of Stat5b-CA.BMDCs into 7- to 8-week-old NOD mice protected the animal from type 1 diabetes, whereas the transfer of Stat5b-CA.BMDCs in which Ezh2 was inhibited have a reduced ability to protect against diabetes." (PMID 32899608, 2020). "We first examined β cell-specific Ezh2 knockout (KO) mice (βEzh2KO) previously reported to exhibit moderate diabetes secondary to defective β cell proliferation." (PMID 29754954, 2018). "Activation of Ezh2 in diabetes, via trimethylation of H3K27, facilitates recruitment of the enzymes responsible for regulation of DNA methylation of the MMP-9 promoter, resulting in its transcriptional activation." (PMID 29261844, 2017). "Ezh2 is also directly involved in DNA methylation, and in diabetes MMP-9 promoter undergoes dynamic DNA methylation." (PMID 29261844, 2017). "Moreover, we report that S-nitrosylation of EZH2 has a vascular protective role at least in a diabetes setting." (PMID 40289112, 2025). "Targeting EZH2 may attenuate oxidative stress and inflammation and, hence, prevent vascular disease in diabetes." (PMID 38580969, 2024).
diabetes (continued). "Whether EZH2-induced H3K27me3 is involved in the abnormal vascular phenotypes observed in the presence of diabetes remains to be elucidated." (PMID 38580969, 2024). "Nevertheless, the role of the CaN/NFATc3 pathway and whether EZH2 may be regulated by the CaN/NFATc3 pathway in diabetes-induced myocardial fibrosis is not fully understood." (PMID 37735624, 2023). "Diabetes can possibly promote myocardial fibrosis by activating of CaN/NFATc3/EZH2 pathway." (PMID 37735624, 2023). "Interestingly, prior evidence has suggested that EZH2 is able to modulate pancreatic beta-cell proliferation and regeneration in diabetes mellitus." (PMID 34802056, 2021). "Importantly, inhibition of Ezh2 in tolerogenic Stat5b-CA.BMDCs reduced their ability to prevent diabetes development in NOD recipient mice." (PMID 32899608, 2020). "Interestingly, injection of Ezh2 inhibitor GSK343-treated BMDCs into NOD mice accelerated diabetes onset in recipient NOD mice." (PMID 32899608, 2020). "The finding that PRC2 loss triggers diabetes-mimicking transcriptional dysregulation and dedifferentiation warrants deeper investigations into relative Ezh1-, Ezh2- and non-methyltransferase-dependent Polycomb activities in the β cell compartment." (PMID 29754954, 2018). "15,16 Ezh2 expression is increased in retinal endothelial cells in diabetes, but, its role in regulating MMP-9 expression remains unclear." (PMID 29261844, 2017). "The results show that the recruitment of Ezh2 is increased at the MMP-9 promoter in diabetes." (PMID 29261844, 2017). "Notably, conditional deletion of Polycomb protein EZH2 in mouse beta-cell determines beta-cell regeneration failure leading to diabetes mellitus." (PMID 24391732, 2013). "Thus, the present study investigated whether CaN/NFATc3/EZH2 pathway plays a role in diabetic myocardial fibrosis, thereby presenting a new direction for prevention and treatment of myocardial fibrosis of diabetic patients." (PMID 37735624, 2023). "Experiments demonstrated that diabetes reduces osteoblastic differentiation potential, downregulates KDM6B demethylase, and upregulates EZH2." (PMID 40725425, 2025). "EZH2 represses the transcription factor Pax6, which controls expression of the antioxidant inhibitor TXNIP, and in diabetes, downregulation of EZH2 promotes oxidative stress." (PMID 37144033, 2023). "Our findings corroborate accumulating evidence illuminating the role of EZH2 and STAT3 in diabetes mellitus-related or neurological diseases." (PMID 34857740, 2021). "In order to further explore the function of PIAS1 in diabetic neuropathy, adenovirus stably overexpressing PIAS1, EZH2, and STAT3 was infected into db/db mice with spontaneous type 2 diabetes mellitus." (PMID 34857740, 2021). "Taken together, we reasonably propose EZH2 interacts with FBW7 and pancreatic cells in diabetes, which would fill the gap of FBW7 in T1D." (PMID 34802056, 2021). "We enrolled 9 patients who were diagnosed with AAGN by renal biopsy and 9 patients who underwent tumor nephrectomies without diabetes or chronic renal disease to assess the expression levels of EZH2 and H3K27me3 via immunohistochemistry (IHC) staining." (PMID 37029114, 2023). "Based on those findings, we demonstrated that CaN/NFATc3/EZH2 pathway may contribute to the process of myocardial fibrosis induced by DM, suggesting that pharmacological inhibition of CaN/NFATc3/EZH2 pathway may become an effective therapeutic strategy against myocardial fibrosis in diabetes." (PMID 37735624, 2023). "As with HRECs, diabetes increased H3K27me3 levels at the MMP-9 promoter by approximately 4-fold, and this was accompanied by an increase in Ezh2 recruitment at the same site of the promoter; accompanying gel picture represents the band intensity on a 2% agarose gel." (PMID 29261844, 2017).
diabetes (continued). "Notably, the phenotype of beta-cell Ezh2 knockout (KO) is distinct from that of Eed KO, being milder and marked by proliferation defects as opposed to beta-cell dysfunction and severe diabetes in Eed KO." (PMID 35602600, 2022). "Consequently, mice lacking Ezh2 in pancreatic β-cells exhibit mild diabetes, suggesting a role for pancreatic Ezh2 in β-cell function." (PMID 33193730, 2020).